NOTCH3 (notch receptor 3)
Diseases named in the same sentence as NOTCH3 in open-access papers (continued):
Sharing a sentence is not in itself a finding about the gene and the disease.
Ascites (1 paper, 2016). Accumulation of fluid in the peritoneal cavity (between the layers of the peritoneum that lines the abdomen). "Higher expression of Notch3 and pS6 was associated with a higher positive rate of ascites; the positive rates of ascites in patients with high, moderate, and low expression of Notch3 and pS6 were 82.1%, 51.9%, and 27.0%, respectively." (PMID 27445438, 2016). "The χ2 test indicated that the expression level of Notch3 and pS6 has a significant positive correlation with ascites in these groups (χ2 = 28.448, p < 0.01)." (PMID 27445438, 2016). "In addition, the occurrence of ascites in patients with a high level of Notch3 and pS6 expression was significantly higher than in the other groups, suggesting that a high level of Notch3 and pS6 expression may be associated with peritoneal implantation and spreading." (PMID 27445438, 2016).
autoimmune disease (1 paper, 2023). A disorder resulting from loss of function or tissue destruction of an organ or multiple organs, arising from humoral or cellular immune responses of the individual to their own tissue constituents. "We hypothesize that these participants would present with more frequent markers of inflammation and diagnoses of autoimmune conditions than a control population, suggesting a connection between cysteine-altering NOTCH3 variants and autoimmune disorders." (PMID 37834922, 2023). "Alternatively, this suggests that uncontrolled upregulation of NOTCH3, as seen in CADASIL, could trigger the immune system and lead to an increased incidence of autoimmune diseases." (PMID 37834922, 2023).
Autoimmunity (1 paper, 2023). The occurrence of an immune reaction against the organism's own cells or tissues. "Other hypotheses include the mutant NOTCH3 protein inherited in CADASIL leading to immune dysregulation and autoimmunity, and uncontrolled inflammation, as seen in autoimmune conditions, leading to increased levels of inflammatory cytokines which induce the activation of NOTCH signaling." (PMID 37834922, 2023).
autosomal dominant polycystic kidney disease (1 paper, 2022). Autosomal dominant form of polycystic kidney disease. "To examine whether Notch3 plays a role in polycystic disease in humans, we analyzed the expression of Notch3 in human biopsies from patients suffering from autosomal dominant polycystic kidney disease (ADPKD) and acquired cystic kidney disease (ACKD)." (PMID 35055068, 2022).
bladder tumor (1 paper, 2017). "Notch3 was detected in 55 out of 59 samples (93.2%) of bladder tumor tissues." (PMID 28416766, 2017).
Brugada syndrome (1 paper, 2023). A genetically heterogeneous condition characterized by complete or incomplete right bundle branch block accompanied by ST elevation in leads V1-V3. "Expression of the Hey2 gene, which is important for heart development and is linked to Brugada syndrome, a rare form of arrhythmia, was downregulated in the Notch3-/- hearts, which as expected also was the case for Notch3." (PMID 37699967, 2023).
carbon monoxide poisoning (1 paper, 2024). A poisoning that is caused by exposure to carbon monoxide. "The impact of high-pressure oxygen on the Notch signaling pathway following severe carbon monoxide poisoning in mice provides insights into the role of NOTCH3 in disease progression." (PMID 39130639, 2024).
cataract (1 paper, 2025). Partial or complete opacity of the crystalline lens of one or both eyes that decreases visual acuity and eventually results in blindness. "Specifically, we observed significant reductions in JAG1 and Notch receptors (Notch1, Notch2, and Notch3) in the LECs of cataract patients." (PMID 39796164, 2025).
cerebral (1 paper, 2021). "The linear mixed effect models showed that the NOTCH3(+) svMCI group had much greater increases in the lacune and cerebral microbleed counts than the NOTCH3(–) svMCI group." (PMID 33716917, 2021).
cerebral artery disease (1 paper, 2019). "However, we found that only NOTCH3 of these screened three genes was associated with cerebral artery disease in previous work." (PMID 31339861, 2019).
cervical squamous cell carcinoma (1 paper, 2024). A squamous cell carcinoma arising from the cervical epithelium. "However, there is no there is no prior study investigating the specific mechanism of the miR-136/Notch3 interaction in cervical squamous cell carcinoma in cervical squamous cell carcinoma." (PMID 38331752, 2024). "Therefore, we hypothesized that WWTR1-AS1 upregulated Notch3 through miR-136 to increase cervical squamous cell carcinoma (CSCC) cell stemness." (PMID 38331752, 2024).
chronic lymphocytic leukaemia (1 paper, 2022). "In chronic lymphocytic leukaemia (CLL), recurrent NOTCH1 mutations were observed at all disease stages, whereas mutations in the paralogs NOTCH2, NOTCH3 and NOTCH4 were rare events with frequencies <1% (NOTCH2 in 0.9%; NOTCH3 in 0.7%; NOTCH4 in 0.6%)." (PMID 36313682, 2022).
clear cell renal cell carcinomas (1 paper, 2022). "Reanalysis of publicly available data from The Cancer Genome Atlas (TCGA) revealed that NOTCH3 mRNA was expressed most strongly in clear cell renal cell carcinomas." (PMID 35055068, 2022).
cleft lip (1 paper, 2024). Congenital defect in the upper lip where the maxillary prominence fails to merge with the merged medial nasal prominences. "Eight significant variants associated with craniofacial malformations such as non-syndromic cleft lip and palate, mandibular prognathism, ocular abnormalities, and tooth defects are found in AXIN2, BMP2, BMP4, NOTCH3, PTCH1, SOX10, and WNT10A." (PMID 38785976, 2024).
colorectal adenocarcinoma (1 paper, 2022). The most common type of colorectal carcinoma. "The high expression of NOTCH3 and SMARCA4 indicates that the patients with colorectal adenocarcinoma are more likely to differentiate into mucinous adenocarcinoma." (PMID 35900231, 2022).
colorectal adenoma (1 paper, 2025). An adenoma that arises from the colon or rectum. "In other cancers, IL‐33 is induced and activated early in the development of colorectal adenomas and regulates the expression of the stemness genes NANOG, NOTCH3, and OCT3/4." (PMID 40860436, 2025).
congenital heart disease (1 paper, 2017). A heart disease that is present at birth. "Variations in NOTCH2, NOTCH3, TTN, TBX4, TBX10, TBX18, and TBXAS1 are associated with congenital heart disease." (PMID 29381953, 2017).
coronary artery disease (1 paper, 2025). "Future studies will explore the association of NOTCH3 mutations with intracranial large arteries, coronary artery disease, and metabolic abnormalities and their associated pathogenesis based on a larger sample." (PMID 41018180, 2025). "Recent studies have found various manifestations of intracranial large artery anomalies, coronary artery disease, and abnormalities in lipid and glucose metabolism in patients with mutation of NOTCH3 gene." (PMID 41018180, 2025). "With the development of diagnostic and experimental techniques, we have identified NOTCH3 mutations in more clinical studies, including anomalies of the large intracranial arteries, coronary artery disease and abnormalities in lipid and glucose metabolism." (PMID 41018180, 2025). "Finally, based on the findings of intracranial large artery anomalies, coronary artery disease and metabolic abnormalities caused by NOTCH3 mutations, we need to revisit the concept of CADASIL disease." (PMID 41018180, 2025). "In conclusion, NOTCH3 mutations may lead to intracranial aortic anomalies, coronary artery disease, and abnormalities in lipid and glucose metabolism through different mechanisms." (PMID 41018180, 2025).
corticotropinomas (1 paper, 2017). "Conversely, in somatotropinomas and corticotropinomas, NOTCH3-positive cells were observed organized in clusters with particularly intense staining in ACTH tumors." (PMID 28915655, 2017).
cystic kidney disease (1 paper, 2022). A congenital or acquired kidney disorder characterized by the presence of renal cysts. "In conclusion, we found that activation of Notch3 in the renal tubular epithelium leads, over time, to the formation of renal cysts and the concomitant decline in renal function." (PMID 35055068, 2022). "Another major result was that activation of Notch3 in tubular epithelial cells resulted in cystic kidney disease and pre-neoplastic lesions." (PMID 35055068, 2022). "We also observed an altered spindle orientation in Notch3-overexpressing mice, which resulted in a multilayered epithelium and protrusions into the cystic lumen in some of the renal cysts." (PMID 35055068, 2022). "Collectively, Notch3 overexpression induced distinct pathological cystic tubular alterations leading to a deterioration of tubular function with decreased ion channel expression, consistent with the development of cystic kidney disease." (PMID 35055068, 2022).
dry eye (1 paper, 2015). "A recent report showed that members of the canonical Notch signaling pathway i.e., Notch1, Notch2, Notch3, Jagged1, Dll1, were significantly down-regulated in dry eye as compared to the non-dry eye conjunctival epithelia." (PMID 26818247, 2015).
ductal breast carcinoma (1 paper, 2015). "In this study, we try to evidence that IL-6 gene expression is upregulated in MS obtained from aggressive ductal breast carcinomas and that IL-6 regulates a Notch-3-dependent signaling pathway that promotes self-renewal and the invasive potentials of normal and tumor MS." (PMID 25881039, 2015). "In conclusion, our data support the hypothesis that IL-6 induces malignant features in Notch-3-expressing, stem/progenitor cells from human ductal breast carcinoma and normal mammary gland." (PMID 25881039, 2015).
Dyskinesia (1 paper, 2022). A movement disorder which consists of effects including diminished voluntary movements and the presence of involuntary movements. "With regard to dopaminergic complications, we found that dyskinesias (27.3% vs. 15.0%; OR = 2.57, p = 0.194) were more common in NOTCH3-variant carriers." (PMID 36570541, 2022).
Dystonia (1 paper, 2015). An abnormally increased muscular tone that causes fixed abnormal postures. "By week 6 post-CCI, Mash1, DCX and Notch3 expression was significantly increased in the ipsilateral dorsal horns and in the ventral horns, suggesting that neurogenesis might also contribute to the motor abnormality (e.g. dystonia) associated with neuropathic pain." (PMID 26223362, 2015).
eosinophilic esophagitis (1 paper, 2017). Eosinophilic esophagitis (EoE) is a chronic, allergic disease of the esophagus characterized clinically by symptoms of esophageal dysfunction (including vomiting, dysphagia, feeding disorders, food impaction and abdominal pain) which persist after treatment with proton pump inhibitors (PPIs). "Potential influence of these factors upon Notch1-mediated cell fates warrants further investigation in SCC as well as squamous epithelia under eosinophilic esophagitis where EMT and Notch3 downregulation are implicated (P.M.C. and H.N., unpublished observation)." (PMID 29170450, 2017).
Familial advanced sleep-phase syndrome (1 paper, 2019). "Genes with vascular and/or glial cell function emerged from investigating syndromes in which migraine is prevalent, such as NOTCH3 in cerebral autosomal dominant arteriopathy with subcortical infarcts and leukoencephalopathy (CADASIL) and CSNK1D in familial advanced sleep phase syndrome (FASPS)." (PMID 30634909, 2019).
gastric intestinal type adenocarcinoma (1 paper, 2020). An adenocarcinoma of the stomach arising on a background of intestinal metaplasia. "In DErrico’s dataset the expression of Notch3 in gastric intestinal type adenocarcinoma was 2.869 times of that in normal tissues." (PMID 32028262, 2020).
Glomerular sclerosis (1 paper, 2020). Accumulation of scar tissue within the glomerulus. "Glomerular sclerosis and severe proteinuria appear in 2-week-old NICD transgenic mice, while Notch3-knockout mice are protected from tubular injury and interstitial collagen deposition induced by unilateral ureteral obstruction (UUO)." (PMID 33149805, 2020). "Notch3 was significantly activated in podocytes in mouse models of FSGS induced by adriamycin injection, and the model animals exhibited increased proteinuria, decreased podocyte numbers, and glomerulosclerosis." (PMID 33149805, 2020). "Additionally, increased glomerulosclerosis, extracellular matrix production by PECs, numbers of activated and profibrotic PECs, expression levels of epithelial-mesenchymal transition (EMT) markers (α-SMA and vimentin), and activation of Notch3 were observed in PECs from aged mice." (PMID 33149805, 2020).
hemorrhage (1 paper, 2022). Loss of blood from the vascular compartment to the exterior or into nonvascular body space as a result of rupture or severance of the blood vessels. "Furthermore, adult Notch3–/– mice exhibit VSMC degeneration in the retina and brain, causing hemorrhage, loss of vessel integrity, and loss of blood-brain-barrier function." (PMID 35998033, 2022).
Hepatitis (1 paper, 2012). Inflammation of the liver. "We have previously shown that Notch3 significantly up-regulated in fibrotic liver tissues of patients with hepatitis." (PMID 23056328, 2012).
heritable pulmonary arterial hypertension (1 paper, 2025). Heritable pulmonary arterial hypertension (HPAH) is a form of pulmonary arterial hypertension (PAH), occurring due to mutations in PAH predisposing genes or in a familial context. "Both pathways induce notch receptor (NOTCH) 2 while inhibiting NOTCH3, thereby promoting the proliferation of PASMCs in heritable pulmonary arterial hypertension (HPAH)." (PMID 40066229, 2025).
IgA nephropathy (1 paper, 2020). "Similar upregulation of Notch3, Jagged2, and YBX1 was also observed in glomeruli isolated from patients with IgA nephropathy." (PMID 33149805, 2020). "The immunohistochemical staining results showed that the healthy human tissue did not exhibit positive staining for Notch3 except in VSMCs; however, in IgA nephropathy, Notch3 staining was increased in glomerular cells, predominantly within the mesangial cells." (PMID 33149805, 2020).
kidney cancer (1 paper, 2016). Primary or metastatic malignant neoplasm involving the kidney. "To this end, we determined the correlation in the expression of PlexinD1 with Notch1 and Notch3 in datasets of prostate, colon, thyroid and kidney cancers." (PMID 27749937, 2016).
left ventricular hypertrophy (1 paper, 2023). Enlargement of the LEFT VENTRICLE of the heart. "Here, we demonstrate that Notch3-/- mice have enlarged hearts with left ventricular hypertrophy and mild fibrosis." (PMID 37699967, 2023). "Here, we report that Notch3-/- mice exhibit left ventricular hypertrophy, cardiomyocyte hypertrophy and mild fibrosis." (PMID 37699967, 2023). "Collectively, these observations suggest that Notch3-/- mice exhibit left ventricular hypertrophy, combined with mild fibrosis." (PMID 37699967, 2023). "In conclusion, the Pdgfbret/ret mouse exhibits left ventricular hypertrophy similar to what is observed in the Notch3-/- mice, but the two mouse models differ with regard to lipid accumulation in the liver." (PMID 37699967, 2023). "Like the Notch3-/- mice, the Pdgfbret/ret mice exhibited enlarged hearts, accompanied by left ventricular hypertrophy." (PMID 37699967, 2023). "The observed switch towards a glycolytic metabolism in the Notch3-/- hearts may therefore be a consequence of the left ventricular hypertrophy." (PMID 37699967, 2023). "Whether the decrease in number of arterioles in the Notch3-/- hearts contributes to the left ventricular hypertrophy remains to be explored." (PMID 37699967, 2023).
lymphoid tumors (1 paper, 2011). "In contrast with Notch3, Tax is able to activate both the alternative and canonical NF-κB pathways, implying that the appearance of lymphoid tumors in HTLV-1 infected is linked to the exclusive activity of Tax." (PMID 21909275, 2011).
malignant glioma (1 paper, 2013). A grade III or grade IV glioma arising from the central nervous system. "We investigated the functional role of NOTCH3 in malignant glioma cell lines to further elucidate the significance of NOTCH3 gene amplification." (PMID 24143218, 2013). "To determine the functional role of NOTCH3 in malignant glioma, we first produced NOTCH3 specific shRNA lentivirus to establish an in vitro model for further experiments." (PMID 24143218, 2013). "Taken together, these data suggest a major role for NOTCH3 in malignant glioma cell proliferation." (PMID 24143218, 2013).
maturity onset diabetes (1 paper, 2024). "Along with TRIM28 and NOTCH3, one of our most interesting discoveries in the ART placentas concerned the prominent downregulation of imprinted DLK1 as well as the pathways of insulin secretion and maturity onset diabetes of the young, which came forth in the DNAm analyses." (PMID 39702541, 2024).
medulloblastoma (1 paper, 2021). A malignant, invasive embryonal neoplasm arising from the cerebellum. "A downregulation of the Notch3 pathway is also observed: in fact the Notch3 pathway interacts with the WNT pathway in the development of the CNS vasculature, and this can partially explain the branched vasculature observed in WNT-medulloblastomas." (PMID 34884457, 2021).
metastatic colorectal cancer (1 paper, 2023).
motor neuron disease (1 paper, 2022). "Two genes in this segment, NOTCH3 and Safb/SAFB1, have been associated with motor neuron disease." (PMID 36107978, 2022).
pancreatic sarcomatoid carcinoma (1 paper, 2025). "Emerging evidence indicates that Notch3 is associated with PD-L1 and co-expressed in pancreatic sarcomatoid carcinoma, suggesting that combined targeting of PD-L1 and Notch3 may represent a promising therapeutic strategy." (PMID 41217541, 2025).
penile squamous cell carcinomas (1 paper, 2022). "A link between penile squamous cell carcinomas and NOTCH3 mutation has not been described so far." (PMID 36564761, 2022).
pituitary tumor (1 paper, 2013). A benign or malignant neoplasm affecting the pituitary gland. "Further study is required to elucidate the exact mechanism of Notch3 signaling in pituitary tumor development and tumorigenesis." (PMID 23426998, 2013). "Another study demonstrated elevated Notch3 mRNA and protein expression in non-functioning pituitary tumors." (PMID 23426998, 2013).
polycystic ovary syndrome (1 paper, 2023). A disorder that manifests as multiple cysts on the ovaries. "A control experiment among patients with polycystic ovary syndrome (PCOS) showed that, compared with individuals without PCOS, the eggs of patients with PCOS extracted high Notch-2 in oocyte complexes; here, Notch-3, Jagged-1, and Jagged-2 gene expression decreased significantly." (PMID 38003436, 2023).
prolactinomas (1 paper, 2017). "There are also few data describing the Notch system in animal models of prolactinomas, even though several components of the Notch pathway such as NOTCH3, ASCL1 and HES1 are altered in human prolactinomas." (PMID 28915655, 2017). "On the other hand, in prolactinomas harbored by lacDrd2KO female mice, not only Notch1 and Notch3 mRNA levels but also NOTCH2-3 membrane and NOTCH1 active domains were highly expressed in knockout mice compared to their control counterparts, the Drd2loxP/loxP mice." (PMID 28915655, 2017).